RAP1A (RAP1A, member of RAS oncogene family)
Diseases named in the same sentence as RAP1A in open-access papers (continued):
Sharing a sentence is not in itself a finding about the gene and the disease.
cancer (continued). "We confirmed that a pulse treatment of YM529 successfully prevented the geranylgeranylation of Rap1A in cancer cells, even when applied for as little as 2 h." (PMID 17043684, 2006). "In addition, we examined clinical data from cancer patient cohorts to assess the link between disruptive RAP1A SNPs and patient outcomes." (PMID 39498560, 2025). "Other studies also showed that RAP1A may be a potential target for cell proliferation, adhesion, and invasion in different types of cancers." (PMID 34178637, 2021). "Although it is not known whether Rap1a directly controls melanogenesis, it has been reported that Rap1a inhibits Akt phosphorylation in cancer cells." (PMID 34831071, 2021). "Rap1a GTPase is known to regulate the migration of both normal cells and cancer cells." (PMID 32102991, 2020). "Taken together, these evidences collectively indicate that RAP1A may be a promising biomarker for cancer diagnosis and treatment." (PMID 30064475, 2018). "In lung cancer, knocking down Rap1A can sensitize cancer cells to chemotherapy." (PMID 25636908, 2015). "Overall, these results indicate that the activity or function of Rap1A may be altered in aggressive cancer cells." (PMID 23405264, 2013). "Rap1a might serve as an alternative target for cancer therapy." (PMID 23565202, 2013). "Then, differential expression analysis was separately performed on RAP1A and TRPM8 transcript levels in each one of the three cancer cohorts." (PMID 35565390, 2022). "In particular, residues E207 and Y240 in the sequence of TRPM8 and Y32 in that of Rap1A are critical for the interaction between the two proteins not only in PC3 cells but also in cervical (HeLa) and breast (MCF-7) cancer cells." (PMID 35565390, 2022). "These suggest that RAP1A, STARD13, SASH1, RECK, and CBFA2T3 had big positive network effects on down-expression of genes in stage-3 cancer." (PMID 33580150, 2021). "Hence, the strong TS genes SASH1, STARD13, RECK, CBFA2T3, RASSF2, RAP1A, and ARHGEF12 can be used as specific biomarkers for diagnosis of NSCLC cancer." (PMID 33580150, 2021). "Seven out of 52 genes (GSTP1, HSP90B1, HSPB1, PFN1, RAP1A, SFN, YWHAZ) were assigned to KEGG pathways in cancer, cell migration and cell cycle, and in signaling networks involved in proliferation, cellular motility, apoptosis, cell adhesion, angiogenesis and genetic integrity." (PMID 30157864, 2018). "However, the essential functional implications of RAP1A SNPs and their role in malignancies like cancer are not fully understood." (PMID 39498560, 2025). "Additionally, when compared across the pan-cancer dataset, GBM had elevated levels of Rap1a compared with other common cancers, although it was not ubiquitously increased across all cancers." (PMID 32102991, 2020).
cardiovascular disease (2 papers, 2021 to 2025). "Based on the findings from this study, reduction, not ablation, of Rap1a could be a potential therapeutic target to reduce the level of AGE/RAGE signaling in diabetic conditions, and possibly reduce the risk for developing cardiovascular disease." (PMID 34067282, 2021).
infection (2 papers, 2015 to 2016). The state of being infected such as from the introduction of a foreign agent such as serum, vaccine, antigenic substance or organism. "The high conservation of RAP-1a across the three isolates from B. motasi-like parasites suggests that rRAP-1a61-1/CT could be a promising common diagnostic antigen that can detect geographically distinct isolates of B. motasi-like infections in sheep." (PMID 27245213, 2016). "In the present study, we cloned and expressed RAP-1a and then detected the presence of antibodies directed against native and recombinant forms of RAP-1a during the course of infection." (PMID 27245213, 2016). "On average, RAP-1a was expressed at sequentially higher levels from week 1 to week 7 post-infection before its levels subsequently decreased." (PMID 27245213, 2016). "To investigate the potential role of Rap1A in osteoblast differentiation, we silenced the expression of endogenous Rap1A by lentivirus-mediated infection with two specific shRNAs (shRNA1-2)." (PMID 26599016, 2015).
neurodegenerative disease (1 paper, 2022). A disorder of the central nervous system characterized by gradual and progressive loss of neural tissue and neurologic function. "Magi2, Kif5b, Sqstm1 and Rap1a are associated neuronal development and neurite outgrowth, and some have previously been implicated in the pathogenesis of neurodegenerative diseases." (PMID 36089582, 2022).
RAP1A also shares sentences with these, for which no sentence is quoted: hepatocellular carcinoma (3 papers); colitis (2); Alzheimer disease (1); blood cancer (1); ductal carcinoma (1); ductal carcinoma in situ (1); gingivitis (1); Hyperglycemia (1); hypertensive heart disease (1); invasive breast carcinoma (1); Lewis lung carcinoma (1); low grade glioma (1); lung (1); macular degeneration (1); metastatic melanoma (1); multiple myeloma (1); multiple sclerosis (1); Myocardial fibrosis (1); myocardial infarction (1); neurodevelopmental disorder (1); neuropathic pain (1); oral cancers (1); osteoporosis (1); osteosarcoma (1); parasitic infections (1); periodontal disease (1); RASopathies (1); renal cell carcinoma (1); small cell lung carcinoma (1); uterine cancer (1).